KLF5 (KLF transcription factor 5)
Diseases named in the same sentence as KLF5 in open-access papers (continued):
Sharing a sentence is not in itself a finding about the gene and the disease.
prostate carcinoma (continued). "Our conclusion is contrary to a previous report that knockdown of HDAC1/2 in the DU145 prostate cancer cell line promotes KLF5 acetylation at K369 but protects KLF5 from degradation." (PMID 35342356, 2022). "miR-153 controls high GS prostate cancer cell proliferation, migration and invasion, possibly by regulating KLF5 expression." (PMID 35683018, 2022). "Most recently, it was reported that the growth of KLF5-K369R overexpression prostate cancer cells in nude mice is faster than WT KLF5 overexpression cells." (PMID 35342356, 2022). "Recently, HDAC3 was shown to interact with KLF5 to promote prostate cancer autophagy in response to docetaxel treatment." (PMID 35342356, 2022). "In prostate cancer cells, the overexpression of miR-153 is necessary to maintain KLF5 silencing, which in turn maintains a high cell proliferation rate." (PMID 35683018, 2022). "KLF5 is a component of another molecular pathway capable of regulating autophagy and docetaxel sensitivity of prostate cancer cells." (PMID 35317831, 2022). "In fact, docetaxel reduces KLF5 expression to prevent cell death induction in prostate cancer cells." (PMID 35317831, 2022). "Our finding of KLF5 and AR opposition provides clues to the molecular determinants of KLF5 functioning as an oncogene vs. tumor suppressor in prostate cancer." (PMID 34737261, 2021). "KLF5 is a key oncoprotein in breast and prostate cancers, where it promotes cell proliferation, survival, and angiogenesis." (PMID 34712671, 2021). "Estrogen promoted the interactions between ERβ, WWP1 and KLF5, leading to promotion of KLF5 degradation in prostate cancer cells." (PMID 34226507, 2021). "Consistently, KLF5 promoted the expression of the basal cytokeratin CK5 in AR-positive prostate cancer cells, which supports a role for KLF5 in lineage plasticity." (PMID 34737261, 2021). "For instance, KLF5 can inhibit the tumorigenesis of human prostate cancer cell lines in nude mice and suppress the proliferation of epithelial cells such as some cancer cell lines in culture." (PMID 34799978, 2021). "Here, the authors show that bone derived TGF-β induces acetylation of KLF5 (Ac-KLF5), and Ac-KLF5 promotes prostate cancer bone metastasis and resistance to docetaxel by upregulating CXCR4." (PMID 33731701, 2021). "Specifically, KLF5 was prone to be deleted in prostate cancer (PRAD) but amplified in gastric cancer (STAD), colorectal cancer (COAD, READ), and head and neck cancer (HNSC)." (PMID 33923166, 2021). "Increasing evidences have revealed that KLF5 is involved in various cancers, such as prostate cancer, non-small-cell lung cancer, and bladder cancer, as well as other diseases." (PMID 32943987, 2020). "Necessity of Klf5 acetylation for castration resistance in BPDLCs also implicates KLF5 acetylation in the development of castration-resistant prostate cancer." (PMID 32081850, 2020). "Our findings suggest that use of one or more currently available agents targeting the TGF-β/acetylated KLF5/BCL2 signaling axis is beneficial to patients with DTX-resistant prostate cancer." (PMID 32685011, 2020). "In an initial study, KLF5 was revealed to be a target of AR and to promote cancer progression in prostate cancer." (PMID 32943987, 2020). "Prostate cancer patient data from two datasets was used to identify the roles of TGF-β, Bcl-2 and KLF5 in prostate cancer." (PMID 32685011, 2020). "In a prostate cancer tissue microarray, we performed immunohistochemistry staining of Bcl-2 and acetylated KLF5." (PMID 32685011, 2020). "Based on previous reports that TGF-β induces acetylation on KLF5 lysine 369 in HaCaT cells 24, 25 and prostate cancer cells 26, we found by in vitro and in vivo studies that TGF-β induced DTX resistance through the acetylation of KLF5." (PMID 32685011, 2020). "To assess this effect of KLF5, we knocked down KLF5 in prostate cancer cells and found that KLF5 knockdown promoted invasive ability of prostate cancer cells in vitro and in vivo." (PMID 32546700, 2020).
prostate carcinoma (continued). "Since high BECN1 level was associated with high-grade prostate cancer (GSE16560), we further investigated the regulation of BECN1 expression by KLF5." (PMID 31534497, 2019). "KLF5 knockdown reduced the sensitivity of prostate cancer cells to docetaxel in vitro and in vivo, and docetaxel treatment decreased the expression of KLF5." (PMID 31534497, 2019). "In summary, our results demonstrated that KLF5 knockdown decreases the sensitivity of prostate cancer cells to docetaxel both in vitro and in vivo." (PMID 31534497, 2019). "To confirm this result, we also examined microarray data profiling of human prostate cancer tissues from the TCGA database to ascertain the correlation between KLF5 expression and Gleason Score in prostate cancer." (PMID 31534497, 2019). "In contrast, in esophageal squamous cell cancer, prostate cancer, and acute myeloid leukemia, KLF5 promotes cell differentiation and inhibits cell proliferation, acting as a tumor suppressor." (PMID 31178864, 2019). "Taken together, these results indicated that docetaxel suppresses KLF5 expression and induces cell autophagy in prostate cancer cells." (PMID 31534497, 2019). "Our results suggest that the deletion and downregulation of KLF5 in prostate cancer lead to decreased response to docetaxel and poorer prognosis." (PMID 31534497, 2019). "It has been reported that chromosome 13q.21 region, which contains the KLF5 gene, is deleted in about 39% human prostate cancers as detected by comparative genomic hybridization analysis." (PMID 31534497, 2019). "Since Bcl-2 plays a role in autophagy, we further analyzed the TCGA database of prostate cancer patients and found the highest percentage of high-grade tumors in the cohort with low KLF5/high Bcl-2 levels." (PMID 31534497, 2019). "We further analyzed the prognosis (recurrence time) of prostate cancer patients from the TCGA database and divided the patients into four cohorts according to the expression levels of KLF5 and BECN1." (PMID 31534497, 2019). "In summary, these results indicated that KLF5 plays an important role in suppressing cell autophagy in prostate cancer cells." (PMID 31534497, 2019). "Consistently, KLF5 gene is deleted in 10% prostate cancers according to the gene copy number assay in the TCGA (The Cancer Genome Atlas, http: //cancergenome.nih.gov/) database." (PMID 31534497, 2019). "On the other hand, KLF5 has been reported to be frequently deleted or downregulated in other kinds of tumors like prostate cancer and acute myeloid leukemia, in which it suppresses cancer cell growth." (PMID 29898734, 2018). "Secondly, conditioned culture media from human prostate cancer cells with deficient or insufficient PTEN and KLF5 knockdown increased tube forming capacity and migration of HuVECs, which are indicative of angiogenic potential." (PMID 25896712, 2015). "For example, 7 of the 25 (28%) prostate cancers with KLF5 deep deletion in the TCGA database and 4 of the 11 (36%) metastatic prostate cancers in another database also have PTEN deep deletion or truncating mutation, as revealed by the cBioPortal analysis." (PMID 25896712, 2015). "We also detected mRNA expression of HIF1α, VEGF and PDGF-B in human prostate cancer cells with altered KLF5 expression." (PMID 25896712, 2015). "Acetylation of KLF5 has been shown to reverse the transcriptional activity of KLF5 in human epidermal cells and prostate cancer cells." (PMID 26372456, 2015). "KLF5 is generally repressed in prostate cancer samples and cell lines and acts as a tumor suppressor via an interaction with ERβ, CBP, or FOXO1." (PMID 26474386, 2015). "In contrast to KLF5 acetylation in epidermal cells and prostate cancer cells, acetylation of Klf5 in ESCs only enhances its transcriptional activity, rather than switching from a transcriptional repressor to an activator." (PMID 26372456, 2015).
prostate carcinoma (continued). "Consistently, knockdown of KLF5 in PTEN-insufficient human prostate cancer cells increased tube formation and migration in HuVECs, enhanced PI3K/AKT activity, and upregulated HIF1α, VEGF and PDGF." (PMID 25896712, 2015). "AR signaling was shown to activate CXCR4 protein expression through KLF5 in prostate cancer cells, propelling chemotactic migration in response to CXCL12, a chemokine abundantly present in the microenvironment and specific sites of metastasis." (PMID 24429391, 2014). "Although KLF5 inhibits cell growth or promotes cell apoptosis in prostate cancer and esophageal squamous cell cancer, it has been reported that KLF5 plays an oncogenic role in other cancers." (PMID 25170806, 2014). "In prostate cancer, KLF5 was found to become expressed downstream of androgen receptor (AR) signaling." (PMID 24429391, 2014). "In fact, KLF5 appears to be not only a direct target gene but also a functional co-factor of AR in the regulation of AR target genes in the AR-positive LNCaP prostate cancer cell line." (PMID 23755247, 2013). "Recently, KLF5 was shown to suppress the tumorigenesis of prostate cancer cells in xenograft models, supporting a tumor suppressor function of KLF5." (PMID 23755247, 2013). "In the AR-positive LNCaP prostate cancer cell line, which has lost one copy of the KLF5 genome, KLF5 appears to be a direct target and functional co-factor of AR in transcriptional regulation of AR target genes." (PMID 23755247, 2013). "The KLF5 gene centers a common region of deletion at 13q21 in human cancers including prostate cancer, suggesting a tumor suppressor function for KLF5." (PMID 23755247, 2013). "The expression pattern of Klf5 in mouse prostate and prostate cancer cell lines suggests that Klf5 plays a similar role in the prostate, and is important in regulating the balance of proliferation and differentiation in prostate epithelial cells." (PMID 23755247, 2013). "Overexpression of KLF5 in prostate cancer cell lines inhibits proliferation; however, KLF5 transcript levels are consistently increased in prostate cancer samples, relative to normal prostate epithelium." (PMID 23372710, 2013). "Androgens promote migration of prostate cancer cells via KLF5-mediated upregulation of CXCR4 expression." (PMID 22074556, 2011). "Previous studies have shown that, in prostate cancer, caveolin-1 and KLF5/SREBP-1 function upstream of FASN." (PMID 20508725, 2010). "Previous study reported that in prostate cancer cells, KLF5 could collaborate with HDAC3 to repress BECN1 transcription." (PMID 40659605, 2025). "To investigate whether SOX9 and KLF5 are drivers of cancer stemness, we overexpressed these two transcription factors in vitro using the prostate cancer cell line 22Rv1 and normal prostatic epithelial cell line RWPE‐1." (PMID 38483933, 2024). "In our most recent study, we found that Ac-Klf5 is essential for proper basal-to-luminal differentiation in the prostate and that loss of Klf5 acetylation in basal progenitor cells results in low-grade PIN, suggesting a role of Klf5 acetylation in prostate cancer progression." (PMID 38781024, 2024). "WWP1 interacts with the PY2 motif of KLF5 (at codon 293-348) to promote its ubiquitination and degradation in breast and prostate cancers, suggesting that WWP1 might promote tumorigenesis via KLF5 downregulation (Fig. 5A3,)." (PMID 38129384, 2023). "The KLF5 expression has been found to be downregulated in prostate cancer." (PMID 38087142, 2023). "Importantly, prostate cancer metastases from the TGF-β-rich bone environment indeed express higher levels of Ac-KLF5 than those from visceral tissues." (PMID 36810084, 2023). "In addition, knocking down KLF5 was reported to desensitize castration-resistant prostate cancer cells to docetaxel by inducing autophagy." (PMID 37391422, 2023).
prostate carcinoma (continued). "According to a recent report that KLF5 could inhibit autophagy in prostate cancer, we performed RT-qPCR to find that BECN1 was negatively correlated with KLF5 in BC." (PMID 35073911, 2022). "We evaluated KLF5 expression at various stages of prostate cancer progression." (PMID 34737261, 2021). "The molecular mechanisms that govern KLF5 functioning as a tumor suppressor in prostate cancer, and an oncogenic factor in other cancers, are currently unknown." (PMID 34737261, 2021). "Remarkably, the acetylation status of KLF5 determines whether this protein will switch from its tumor suppressor function to tumor promoter in prostate cancer cells." (PMID 33572160, 2021). "We identified two distinct mechanisms that up-regulate KLF5 expression in prostate cancer cells." (PMID 34737261, 2021). "Androgen-dependent prostate cancer cell lines LNCaP and VCaP also expressed low levels of KLF5." (PMID 34737261, 2021). "In addition, KLF5 was inactivated by the hemizygous deletion in prostate cancer, and re-expression of KLF5 inhibits cell growth in vitro." (PMID 33923166, 2021). "Downregulation of KLF5 desensitizes prostate cancer cells to chemotherapy." (PMID 34712671, 2021). "For example, in the Hippo pathway, WWP1 executes its tumorigenic function by targeting LAST1 for degradation, while two other components of this pathway, YAP and TAZ, antagonize WWP1-mediated degradation of KLF5 and consequently promote growth and metastasis of some breast and prostate cancers." (PMID 34712671, 2021). "Moreover, as a dual functional growth factor, TGF-β induces growth inhibition via acetylation on KLF5 lysine 369 in HaCaT cells 24, 25 and prostate cancer cells." (PMID 32685011, 2020). "The KLF5-AR interaction could provide a therapeutic opportunity for the treatment of prostate cancer." (PMID 32245249, 2020). "Accordingly, these results suggest that the TGF-β/acetylated KLF5/BCL2 signaling axis mediates DTX resistance in prostate cancer and that targeting this signaling axis might be a novel therapeutic approach for the treatment of chemo-resistant prostate cancer." (PMID 32685011, 2020). "In this study, we tested whether and how KLF5 plays a role in the function of AR signaling in prostate cancer cells." (PMID 32245249, 2020). "Herein, we analyzed KLF5 expression in TCGA and GEO database, as well as prostate cancer tissue microarray, and found that KLF5 expression significantly decreased in prostate cancer accompanying with tumor progression; moreover, KLF5 downregulation was associated with shorter survival of patients." (PMID 32546700, 2020). "It is still unclear whether TGF-β-induced KLF5 acetylation is required for DTX resistance of prostate cancer cells." (PMID 32685011, 2020). "Meanwhile, other cancers, including colon cancer, prostate cancer and bladder cancer, etc., with high KLF5 expression may also benefit from FZU-00,003 treatment." (PMID 32025209, 2020). "Our findings further suggest that KLF5 acetylation could be an alternative drug target for overcoming DTX resistance in prostate cancer." (PMID 32685011, 2020). "Using multiple patient datasets with expression profiles and clinicopathological information, we also found that TGF-β and higher KLF5 expression correlated with poor prostate cancer patient survival; and showed that BCL2 was a potential biomarker with both prognostic and predictive functions." (PMID 32685011, 2020). "To explore whether KLF5 is involved in cell sensitivity to docetaxel in prostate cancer cells, we knocked down KLF5 and treated cells with docetaxel at different concentrations." (PMID 31534497, 2019). "KLF5 is frequently deleted or downregulated in prostate cancer." (PMID 31534497, 2019). "In prostate cancer, the KLF5 gene is frequently deleted and downregulated." (PMID 31534497, 2019).
prostate carcinoma (continued). "We next transiently transfected a pH-sensitive LC-3 construct consisting of a tandem fusion of the acid-insensitive mRFP and the acid-sensitive EGFP into prostate cancer cells to monitor the effects of KLF5 knockdown on the formation of autophagosome and its matured form of autolysosome." (PMID 31534497, 2019). "Our results indicate that in prostate cancer, docetaxel treatment represses KLF5 expression through AMPK/mTOR/p70S6K signaling pathway, which may lead to increase of BECN1, induction of cell autophagy, and promotion of cell survival." (PMID 31534497, 2019). "Thus, repression of BECN1 and cell autophagy was critical for KLF5 to increase the sensitivity of prostate cancer cells to docetaxel." (PMID 31534497, 2019). "Moreover, KLF5 protein is degraded by the WWP1 E3-ligase-mediated proteasome pathway in prostate cancer cells." (PMID 31534497, 2019). "We found that KLF5 downregulation may result in low sensitivity to docetaxel in prostate cancer cells." (PMID 31534497, 2019). "In the present study, we analyzed the correlation between KLF5 expression and prostate cancer prognosis and examined whether KLF5 downregulation increased cell sensitivity to docetaxel in prostate cancer cells in vitro and in vivo." (PMID 31534497, 2019). "In prostate cancer, docetaxel treatment repressed KLF5 expression via AMPK/mTOR/p70S6K signaling pathway, which may lead to increased BECN1 expression, induction of cell autophagy and promotion of cell survival." (PMID 31534497, 2019). "KLF5 is frequently deleted and down-regulated in prostate cancer." (PMID 31534497, 2019). "While miR-138 appeared to be downregulated by Klf5 deletion in mouse prostate tumors, it was unaltered by KLF5 loss in human prostate cancer cells (data not shown)." (PMID 25896712, 2015). "And modification of KLF5 acetylation status also converted its roles in prostate cancer." (PMID 26544730, 2015). "We found that in Pten-null mouse prostate tumors, deletion of Klf5 significantly promoted angiogenesis, and conditioned media from human prostate cancer cells with modulated KLF5 expression affected tube formation and migration of human umbilical vein endothelial cells (HuVECs)." (PMID 25896712, 2015). "The opposing functions of unAc-KLF5 and Ac-KLF5 in epidermal cells and prostate cancer cells led us to hypothesize that acetylation of Klf5 may switch the transcriptional output during the segregation of the ICM and the TE." (PMID 26372456, 2015). "Overexpression of KLF5 in human prostate cancer cells showed a consistent effect on HuVECs." (PMID 25896712, 2015). "To further test the role of KLF5 in angiogenesis, we determined whether changes in KLF5 expression in human prostate cancer cells directly modulate endothelial cell behaviors such as tube formation and migration, both of which are indicative of angiogenesis." (PMID 25896712, 2015). "Overexpression of KLF5 suppressed the growth of prostate cancer cell line DU145 and 22RV1." (PMID 26544730, 2015). "We also used transient transfection of siRNAs to knock down KLF5 and adenoviral infection to transiently express KLF5 in the two prostate cancer cell lines, and confirmed that knockdown and overexpression of KLF5 respectively increased and decreased the expression of HIF1α." (PMID 25896712, 2015). "In this study, we performed histological and molecular analyses in mouse prostate tumors and human prostate cancer cells with the deletion or knockdown of KLF5 and PTEN, and obtained multiple lines of evidence suggesting the role of KLF5 loss in tumor angiogenesis." (PMID 25896712, 2015). "Our recent study showed that interruption of KLF5 acetylation also promotes prostate cancer growth." (PMID 25896712, 2015). "Acetylation of human KLF5 at lysine 369 switches its transcriptional activity from a repressor to an activator for the p15 gene in the HaCaT epidermal epithelial cell line and prostate cancer cells." (PMID 26372456, 2015).